IL2RA (interleukin 2 receptor subunit alpha)
Diseases named in the same sentence as IL2RA in open-access papers (continued):
Sharing a sentence is not in itself a finding about the gene and the disease.
type 1 diabetes (continued). "In humans, IL2RA gene polymorphisms affecting CD25 function have been associated with multiple sclerosis, type 1 diabetes, juvenile idiopathic arthritis, or lymphoproliferative-associated immunodeficiency, highlighting the dependency of Treg in this receptor to exert their function." (PMID 27242797, 2016). "None of the polymorphic variants of the IL2RA gene found associated with Type 1 Diabetes (T1D) was shown to have a functional effect." (PMID 23874506, 2013). "Other gene polymorphisms, interleukin-2 receptor alpha (IL2RA), forkhead box P3 (FOXP3), thyroglobulin (TG), CD25, CD40, CLEC16A, and FCRL3, among others, have been found to contribute to both thyroid autoimmunity and type 1 diabetes (Frommer and Kahaly, 2021)." (PMID 41268326, 2025). "This is supported by our single-cell-level results, in which we observed evidence for co-localisation between IL2RA expression and the risk of type 1 diabetes only in CD8+ central memory T cells (eQTL of Tregs were not available as they were not distinguished from other T cells)." (PMID 39271518, 2024). "Interestingly, a recent integrative analysis of genetic association, functional genomics data and protein–protein networks identified DGKQ as a potential novel type 1 diabetes therapeutic gene target along with other novel and known targets, e.g., IL2RA, IL6ST, IL6R and TYK2." (PMID 35142878, 2022). "Furthermore, our co-localisation results suggest that associations between whole-blood IL2RA and IL6R expression and the risk of type 1 diabetes are unlikely to be caused by LD with a genetic variant that primarily influences the reading of other genes in the vicinity of IL2RA or IL6R loci." (PMID 39271518, 2024). "In the case of SNP group 1 of the IL2RA type 1 diabetes locus, three of the SNPs differentially bind common transcription factors (rs12722508*A, rs12722522*C and rs41295061*A) implying that there may be more than one SNP within SNP group 1 affecting IL2RA transcription." (PMID 23028375, 2012). "Furthermore, our Mendelian randomisation estimates represent the influence of small changes in IL2RA, IL6R and TYK2 expression during the entire life course before the diagnosis of type 1 diabetes." (PMID 39271518, 2024). "Only five type 1 diabetes loci with compelling evidence had been identified before the advent of GWA studies: the HLA class II genes on chromosome 6p21; the insulin gene (INS) on 11p15; CTLA4 on 2q33; PTPN22 on 1q13; and, IL2RA/CD25 on 10p15." (PMID 18045485, 2007).
multiple sclerosis (29 papers, 2009 to 2025). A progressive autoimmune disorder affecting the central nervous system resulting in demyelination. "Genetic studies decoding the complex genetic heritage of MS have established that the single nucleotide polymorphism (SNP) rs2104286 in the first intron of the IL2RA gene increases the risk of developing multiple sclerosis." (PMID 34386002, 2021). "Xia, Qin, and Zhao (2018) found that the loci of IL2RA rs2104286 and rs12722489 are closely associated with increasing risk of multiple sclerosis in the Han and Hui nationalities." (PMID 31134763, 2019). "International Multiple Sclerosis Genetics Consortium initially reported rs12722489 as the strongest MS-associated SNP in the IL2RA locus in 2007." (PMID 28234966, 2017). "We have previously fine-mapped genetic causal variants for T1D and multiple sclerosis (MS) in the IL2RA region, identifying five groups of SNPs in intron 1 and upstream of IL2RA, each of which is likely to contain a single disease-causal variant." (PMID 28870212, 2017). "We then applied it to fine map the established multiple sclerosis (MS) and type 1 diabetes (T1D) associations in the IL-2RA (CD25) gene region." (PMID 26106896, 2015). "Further support has come from recently conducted genome-wide association studies of RA and multiple sclerosis (MS) showing that the same SNP, rs2104286, which lies within intron 1 of the IL2RA/CD25 gene, is associated with both diseases." (PMID 19116909, 2009). "Allele distribution and frequency of IL2RA SNPs in patients with multiple sclerosis and healthy controls." (PMID 19125193, 2009). "Considering available disease association data, transcription-factor-binding site prediction and epigenetic data, we chose to focus on rs12722489, an SNP from IL2RA gene associated with rheumatoid arthritis, multiple sclerosis, Crohn's disease, and ulcerative colitis." (PMID 28234966, 2017). "IL2RA variants are known to protect against multiple sclerosis, diabetes mellitus and RA." (PMID 26350950, 2015). "As the associated SNPs analyzed in a genome wide association scan (GWAS), candidate-gene association study in MS and T1D were not the same we considered interesting to test if the TID-associated SNPs in the IL2RA region were also associated with multiple sclerosis (MS) in our cohort of MS patients." (PMID 19125193, 2009). "Finally, seven SNPs near IL2RA (10p15.1) have been reported as associated with RA, T1D, multiple sclerosis, alopecia areata, primary sclerosing cholangitis, and plasma t-tau levels, with other SNPs in the region being associated with several immune-related traits." (PMID 29309429, 2018). "Single nucleotide polymorphisms (SNPs) in or near the IL2RA gene, that encodes CD25, have been associated with increased risk of several immune-mediated diseases —including multiple sclerosis (MS)." (PMID 31242590, 2019). "Single nucleotide polymorphisms (SNPs) in or near the IL2RA gene, that encodes the interleukin-2 (IL-2) receptor α (CD25), are associated with increased risk of immune-mediated diseases including multiple sclerosis (MS)." (PMID 31242590, 2019). "Recent association studies in multiple sclerosis (MS) have identified and replicated several single nucleotide polymorphism (SNP) susceptibility loci including CLEC16A, IL2RA, IL7R, RPL5, CD58, CD40 and chromosome 12q13–14 in addition to the well established allele HLA-DR15." (PMID 20368992, 2010). "Finally, we show that colocalisation of our associations with disease risk signals can suggest aetiological cell-types—variants in IL2RA and ITGA4 respectively mirror the known effects of daclizumab in multiple sclerosis and vedolizumab in inflammatory bowel disease." (PMID 37596262, 2023). "We identified a model for multiple sclerosis containing two variants, neither of which was found through a stepwise search, and functionally linked both of these to the neighbouring candidate gene, IL2RA, in independent data." (PMID 26106896, 2015).
diabetes (25 papers, 2009 to 2025). "This is reflected by the increased induction of chemokine transcripts by plasma of siblings with low HLA risk and individuals with diabetes, and elevated induction of regulatory transcripts (IL2RA, CBLB, SMURF1, SMURF2, SKI) by plasma of siblings with high HLA risk and unrelated control individuals." (PMID 30167736, 2018). "This is important because it is still unclear whether defects in the IL2/IL2R pathway play a significant role in most cases of human diabetes; although a gene variant of IL2RA (CD25) has been associated with T1D risk in people, it is protective but rare." (PMID 29527189, 2018). "In conclusion, we identify significant associations between 4 SNPs (NLRP1 rs12150220, IL2RA rs11594656, CLEC16A rs725613 and APOA5 −1131T/C) and diabetes." (PMID 23922971, 2013). "The first example involves basiliximab, IL2RA, and diabetes." (PMID 30952858, 2019). "Moreover, T/T genotype of analyzed IL2RA SNP was more frequent in T1D patients compared to healthy children as well as AITD children, indicating strong susceptibility of T allele and T/T genotype to diabetes development." (PMID 32974248, 2020). "TGF-β and IL18 in people without diabetes and TNF-α and IL2RA in people with diabetes were independent predictors of SRA1 expression." (PMID 34685582, 2021). "Besides, TGF-β and IL18 independently predicted the SRA1 expression in non-diabetics as well as in the total (diabetic and non-diabetic) study population, while TNF-α and IL-2RA were the independent predictors of SRA1 only in people with diabetes." (PMID 34685582, 2021). "TGF-β/IL18 independently predicted the SRA1 expression in people without diabetes and in the total study population, while TNF-α/IL-2RA predicted SRA1 only in people with diabetes." (PMID 34685582, 2021).
melanoma (19 papers, 1994 to 2025). A malignant, usually aggressive tumor composed of atypical, neoplastic melanocytes. "Interleukin-2 receptor alpha chain (IL2RA) was predominantly targeted in melanoma, with moderate targeting in other cancers." (PMID 39439803, 2024). "And regulatory T‐cell proportion was indeed critically elevated in metastatic melanoma relative to primary melanoma, as well as in highly expressed IL2RA, IL2RG, IL7R, and IFNG group than their respective counterparts." (PMID 34159752, 2021). "Another relevant finding in this study was that overexpressed Treg cells in metastatic melanoma as compared with that in primary melanoma, were the pivotal intermediate components by which IL2RA, IL2RG, IL7R, and IFNG exert their immunosuppressive effect." (PMID 34159752, 2021). "A tetrad of IL2RA, IL2RG, IFNG, and IL7R genes were determined as hub genes and verified by qRT‐PCR, which were significantly associated with unfavorable prognosis in melanoma." (PMID 34159752, 2021). "Overexpressed IL2RA, IL2RG, IFNG, and IL7R were identified as the hub genes associated with melanoma metastasis, and may promote melanoma progression through activation of JAK—STAT signaling pathway." (PMID 34159752, 2021). "Up-regulated IL2RA was also found in tumor of lung, prostate, breast and melanoma, and thus, could serve as a marker of prognosis and immunoreaction." (PMID 34888353, 2021). "Moreover, elevated expression of IL2RA might contribute to metastasis and unfavorable prognosis of melanoma via regulation of JAK-STAT signaling pathway and regulatory T-cells in the tumor microenvironment." (PMID 40864319, 2025). "Several studies have demonstrated that elevated levels of IL2RG as well as genes such as IL2RA, IL7R and IFNγ can promote melanoma metastasis by increasing intratumoral regulatory T cells through activation of the JAK-STAT signaling pathway." (PMID 40096084, 2025). "Collectively, our findings underscored the core position of IL‐2RA, IL‐2RG, IFNG, IL‐7R, and JAK—STAT pathway in melanoma metastasis." (PMID 34159752, 2021). "Our study revealed that IL2RA、IL2RG, IFNG, and IL7R were hub genes in melanoma metastasis and involved in JAK—STAT signaling pathway that was identified as an central signaling pathway in metastatic melanoma, which was rarely illustrated in previous studies." (PMID 34159752, 2021). "IL2RA, IL2R, IFNG, and IL7R were also significantly upregulated in melanoma tissues relative to normal tissues, and had a critically positive correlation to unfavorable prognosis in melanoma." (PMID 34159752, 2021). "Elevated IL2RA, IL2RG, IL7R, and IFNG expression may play a central role in promoting melanoma metastasis through up regulation of intratumoral regulatory T—cell proportion mainly by activation of JAK—STAT signaling pathway." (PMID 34159752, 2021). "Elevated IL2RA, IL2RG, IL7R, and IFNG expression may play a central role in promoting melanoma metastasis via increase in intratumoral regulatory T cell proportion, mainly by activation of the JAK–STAT signaling pathway." (PMID 34159752, 2021). "To investigate whether the distinction also exists between normal and melanoma tissue, we tested the tetrad of IL2RA, IL2R, IFNG, and IL7R transcriptional expression between normal samples and melanoma samples with RT‐PCR, and observe the same expression pattern as expected." (PMID 34159752, 2021).
Crohn disease (14 papers, 2013 to 2025). A gastrointestinal disorder characterized by chronic inflammation involving all layers of the intestinal wall, noncaseating granulomas affecting the intestinal wall and regional lymph nodes, and transmural fibrosis. "A research suggested that an IL2RB single-nucleotide polymorphisms (SNPs) genotyped (rs743776) was significantly associated with Crohn’s disease, while IL2RA SNPs genotyped (rs4749924 and rs706778) were significantly associated with ulcerative colitis." (PMID 37063924, 2023). "The downregulated IL2RA expression is associated with the development of Crohn's disease and rs61839660-T was previously shown to downregulate IL2RA expression by reducing affinity for the MEF2 factors." (PMID 35446421, 2022). "In order to reinforce this role, a relevant meta-analysis confirmed IL2RA as a susceptibility gene for Crohn’s Disease, which shares genetic risk factors with leprosy." (PMID 30540075, 2018). "Other SNPs in the IL2RA locus are associated with Crohn’s disease, Grave’s disease, vitiligo, and alopecia areata." (PMID 24376757, 2013). "The single nucleotide polymorphism [SNP] rs61839660, located within IL2RA [CD25], has been associated with the development of Crohn’s disease [CD]." (PMID 34120187, 2021).
leukemia (14 papers, 2009 to 2025). A malignant (clonal) hematologic disorder, involving hematopoietic stem cells and characterized by the presence of primitive or atypical myeloid or lymphoid cells in the bone marrow and the blood. "Some were already associated with T-CD8+ leukemias (Il2ra; and Pdgfrb) and others were associated with other types of T-leukemias or cancer (Irf4, Hrb, Depdc6, Als2cl, Tle4 and Cdc42ep3), thus validating our approach." (PMID 23902727, 2013). "In two genetically modified mouse models of AML, IL2RA hampered cell differentiation, facilitated stem cell-like characteristics, and was essential for leukemia development." (PMID 38022627, 2023). "Some published results showed that IL2RA was abnormally expressed in a few types of cancers including head and neck, leukemia, breast, lymphoma, lung and prostate." (PMID 35675043, 2022). "Among the negatively associated genes, several genes including PAX2, IL2RA, SOX11, and PAK7 played as oncogenes in leukemia." (PMID 32209730, 2020). "Some of these genes were already known to be involved in T-CD8+ leukemias: Il2ra (expressed in primary leukemia cells from a patient with T-CD8+ prolymphocytic leukemia)." (PMID 23902727, 2013). "For example, F2RL3 and IL2RA are both involved in inflammation and immune regulation, suggesting they may work together to shape the leukemia microenvironment, potentially contributing to immune suppression and tumor progression." (PMID 40506993, 2025). "Although the percentage of leukemia blasts varies from 20 to 99% in the diagnostic bone marrow specimens of this study group, IL2RA expression level was independent of the blast percentage (p = 0.626, Spearman r = − 0.0679)." (PMID 31171000, 2019). "Overexpression of human FST317 and FST344 isoforms enhanced clonogenicity and leukemia engraftment in xenotransplantation model via RET,IL2RA, and CCL5 upregulation." (PMID 32134197, 2020). "FST upregulated expression of RET, IL2RA, and CCL5 that collectively potentiated MAPK signaling and promoted leukemia growth in vitro and in vivo." (PMID 32134197, 2020). "A MET-1 NOD/SCID mouse model was also used to investigate the anti-leukemic effects of specific antibodies targeting IL-2R whereby HAT, murine anti-Tac (MAT), and 7G7/B6, all of which targeting IL-2Rα, significantly delayed leukemia progression resulting in enhanced survival." (PMID 29643841, 2018).
lymphoma (14 papers, 2013 to 2025). A malignant (clonal) proliferation of B- lymphocytes or T- lymphocytes which involves the lymph nodes, bone marrow and/or extranodal sites. "IL2RA is a cytokine receptor of the IL2R family, which is expressed in many types of cancers, including leukaemia, lymphoma, lung cancer, breast cancer, head and neck cancer and prostate cancer." (PMID 32616892, 2020). "An analysis of a representative dataset (Salaverria lymphoma) revealed that MME expression levels were significantly higher in the GCB subtype than those in the ABC subtype and that IL2RA, ETV6, and CCND2 expression levels were higher in the ABC subtype than those in the GCB subtype." (PMID 29992138, 2018).
viral infection (14 papers, 2010 to 2025). "Additionally, defects or variants in IL2RA may confer susceptibility to viral infections and different types of leishmaniasis, including visceral and cutaneous forms." (PMID 39859044, 2025). "Transcription factor TCF1 is expressed at an extremely high level in Tfh cells post-viral infection and exerts crucial roles in generation, maintenance, and effector functions of Tfh cells by repressing Prdm1 and Il2ra and promoting Bcl6 expression." (PMID 33595435, 2021). "Apart from this similarity, different virus infection pathways owned their unique genes, with STAT1,RSAD2 and IRF9 in the influenza A pathway,IL-2RA,IL-2RB and CD40 in the HTLV-1 infection pathway, HCFC1, MAP3K7, SOCS3, IRF9, HMGN1, and FAS in the herpes simplex infection pathway." (PMID 35795668, 2022). "However, the differentiated Il2Ra−/− antigen-specific SLECs express high levels of Blimp-1, indicating that IL-2 signaling is not essential for Blimp-1 expression but is required for its optimal expression in CD8+ T cells during virus infection." (PMID 28732506, 2017). "Additional host factors that were significantly enriched include those described for other viral infections, such as negative-stranded RNA virus vesicular stomatitis virus (VSV) (ARFRP1, SYS1, and YKT6) and the human immunodeficiency virus (HIV) (SRP14, DYRK1A, and IL2RA) (33, –, 37)." (PMID 35502904, 2022).
asthma (12 papers, 1995 to 2026). "IL7R, a component of the TSLP receptor, as well as ICOS and IL2RA, genes important in type 2 inflammatory responses, were increased in females with asthma compared to males with asthma." (PMID 41508394, 2026). "For example, we provide supporting evidence for a role of IL4R in asthma, IL2RA in thyroid dysfunction, and IL12B in psoriasis, as well as many cellular phenotypes, such as Transferrin receptor protein 1 (encoded by TFRC) in mean corpuscular hemoglobin." (PMID 32628676, 2020). "Given the association between eosinophils and asthma, it is worth noting that IL1RL1, IL1RL2, IL2RA, and IL4R are all linked to ‘Eosinophil count’ and ‘Eosinophil percentage’ in GeneAtlas." (PMID 32628676, 2020). "Using GeneAtlas data, our analysis finds 5 proteins—all interleukin receptors—whose levels causally contribute to asthma disease risk: IL1RL1, IL1RL2, IL2RA, IL4R, and IL6R." (PMID 32628676, 2020). "Interleukin-2 receptor alpha (IL2RA) is integral to T-cell activation and regulatory T-cell maintenance; dysregulation of IL2RA has been documented in asthma and chronic obstructive pulmonary disease (COPD) as part of the shared inflammatory cytokine network seen across chronic lung diseases." (PMID 40868449, 2025). "Prior links between these proteins and asthma or atopy exist (IL1RL1 and IL1RL2, IL2RA, IL4R, and IL6R), albeit not necessarily strong evidence for a causal link." (PMID 32628676, 2020).
sarcoidosis (12 papers, 2012 to 2024). Sarcoidosis is a multisystemic disorder of unknown cause characterized by the formation of immune granulomas in involved organs. "Of the 31 TCR/JS/CCR-gene signature genes, 8/31 genes were cited in the sarcoidosis literature with CD28, IFNG, IL7R, AKT3, IL2RA, IL2RB, and STAT4 demonstrating a robust relationship with these terms." (PMID 22984568, 2012).
Sepsis (12 papers, 2018 to 2024). Sepsis is defined as life-threatening organ dysfunction caused by a dysregulated host response to infection. "In addition, the expression of FOXP3, CTLA4, TIGIT, TNFRSF18, and IL2RA, key functional genes of Tregs, was increased in the E-SEP group, suggesting that the immunosuppressive effect of Tregs was enhanced in the elderly with sepsis." (PMID 38909272, 2024).